ASXL1 (ASXL transcriptional regulator 1)
Diseases named in the same sentence as ASXL1 in open-access papers (continued):
Sharing a sentence is not in itself a finding about the gene and the disease.
tumor (continued). "Loss of ASXL1 leads to the retention of H2AK119ub1 at the regulatory loci of INK4B and PTEN and thereby the inactivation of these two well-known tumor suppressor genes in response to oncogenic signals, supporting ASXL1 as a tumor suppressor." (PMID 33796551, 2021). "Gain of function of ASXL1 confers worsened prognosis and promotes tumor growth of ACC." (PMID 34536950, 2021). "Moreover, KMT2D positively regulates the enhancer of the tumor suppressor gene IGFBP5 for melanoma suppression and the enhancers of several tumor suppressor genes (e.g., Socs3, Asxl1 and Arid1A) for lymphoma suppression." (PMID 34194626, 2021). "Not only can these clones be statistically explained with allele dropout, but they also do not fit with a model of serial mutation acquisition predicted by the presence of the NRAS, ASXL1, and IDH2 triple-mutant clone comprising 64% of the tumor at this time point." (PMID 30087104, 2018). "SDHA encodes a mitochondrial enzyme; its amplification may alter cellular metabolism through changes in succinate and α-ketoglutarate levels, potentially influencing the activity of epigenetic regulators such as TET2 and ASXL1, and immune modulation within the tumor microenvironment." (PMID 41373665, 2025). "While ASXL1 and SRSF2 mutations may reflect age-related clonal hematopoiesis, SETBP1 is more strongly associated with secondary AML, CMML, and aCML—often co-occurring with ASXL1 and SRSF2 in those neoplasms." (PMID 41278291, 2025). "Although not proven on a functional level, one could assume that the ASXL1 constitutional variant found in our patient potentially plays a role in tumor development, given its association to other neoplasia as well as the damaging properties of the missense variant." (PMID 32519264, 2021). "Both silencing of ASXL1 and EDP-M regimen significantly inhibited tumor growth of NCI-H295R cells, whereas addition of ASXL-KD further inhibited tumor growth." (PMID 34536950, 2021). "In contrast, p-eIF2α was predicted to negatively regulate tumor suppressors like the homeobox protein HOXA10, estrogen-related receptor alpha (ESRRA), polycomb group protein ASXL1, and mitofusin 2 (MFN2) function 43–46." (PMID 34330898, 2021). "Supporting the tumor suppressive effects of TXNIP and MAGI1, we found that knockdown of TXNIP or MAGI1 in ASXL1+/− K562 cells led to increased proliferation and higher cell viability under serum deprivation." (PMID 32683582, 2021). "It has been previously addressed that depleted ASXL1 might be related to lymphatic invasion of CRC, which suggests that ASXL1 is likely to function as a tumor suppressor in CRC." (PMID 35586041, 2022). "We then verified the expression level of KMT2C, ASXL1, and MCM8 in CCA using the GEPIA database and found that all of the three genes, especially ASXL1 (p < 0.05) and MCM8 (p < 0.05), were overexpressed in tumor tissues." (PMID 32010606, 2019). "Here we report that ASXL2 is required for normal haematopoiesis with distinct, non-overlapping effects from ASXL1 and acts as a haploinsufficient tumour suppressor." (PMID 28516957, 2017). "Furthermore, APC (p < 0.0001), ASXL1 (p < 0.0001), DNMT3B (p = 0.001), PARP4 (p = 0.002), MET (p = 0.01), TOP1 (p = 0.01), KDR (p = 0.01), SRC (p = 0.01), PAK1 (p = 0.015), ALK (p = 0.02), and MYC (p = 0.03) alterations were found to be more common in tumor samples from AO mCRC patients." (PMID 33194656, 2020).
hematological malignancies (38 papers, 2012 to 2026). "These recurrent genetic lesions strongly support the notion that ASXL1-CH represents a risk factor for progression to hematologic malignancies." (PMID 40773119, 2025). "Of other hematologic malignancy-associated variants, ASXL1 was mutated in 5 of 144 (3.5%) and SF3B1 in 2 of 144 (1.4%) patients." (PMID 40179146, 2025). "Most ASXL1 mutations detected in CH and hematological malignancies are frameshift or nonsense mutations in the last exon, generating a C-terminally truncated form of ASXL114,15,17–21." (PMID 33758188, 2021). "Both loss of Asxl1 and transgenically expressed truncated Asxl1 induce severe hematopoietic diseases in mice." (PMID 33483612, 2021). "ASXL1 has well-known roles in histone modification and as a putative tumor suppressor gene that is often reported to be mutated in hematological malignancies." (PMID 28452984, 2017). "Although ASXL1 is primarily associated with hematological disorders, its role in regulating cell proliferation and gene expression may impact vascular smooth muscle cells and inflammatory responses, thereby influencing plaque stability." (PMID 39450006, 2024). "However, because DNMT3A and ASXL1 often contain somatic mutations in a variety of adult hematologic malignancies, we chose to exclude these variants from subsequent analyses." (PMID 37762649, 2023). "Based on available evidence, missense germinal mutations in ASXL1 might act as a risk factor for developing hematological malignancies; topics such as penetrance or anticipation can be discussed only when a much larger number of cases have been studied." (PMID 36035165, 2022). "ASXL1 mutations have been previously observed in a variety of hematological malignancies in humans." (PMID 34202213, 2021). "Mutations in genes like ASXL1 and TET2 are often mutated in the elderly and are associated with clonal hematopoietic expansion, with a high risk of developing hematologic malignancies." (PMID 41514668, 2026). "Here, we show that genetic inactivation of Asxl1 and Ezh2 in murine hematopoietic stem/progenitor cells results in highly penetrant hematological malignancies as observed in corresponding human diseases." (PMID 40561338, 2025). "Previous research has shown that ITP patients harboring mutations in genes such as DNMT3A, TET2, ASXL1, BCOR, PIGA, and U2AF1 tend to progress into other clonal hematologic disorders, leading to treatment ineffectiveness." (PMID 40574285, 2025). "This review provides an overview of the latest studies on ASXL1-CH and the relationship between ASXL1-CH and non-hematological diseases." (PMID 40773119, 2025). "CH is typically defined by pathogenic driver mutations associated with hematological malignancies, most commonly in the epigenetic regulators DNMT3A, TET2, and ASXL1, which collectively account for 90% of CH cases." (PMID 37083525, 2023). "Although additional sex combs-like 1 (ASXL1) has been extensively described in hematologic malignancies, little is known about the molecular role of ASXL1 in organ development." (PMID 30389914, 2018). "Although previous studies have mainly focused on the physical interaction between ASXL1–3 and BRD4 and the biological significance of truncated ASXL1 in hematological malignancies, the epigenetic role of this interaction in regulating target genes and histone acetylation needs further exploration." (PMID 38791157, 2024). "Recent studies using mice expressing an ASXL1 mutant demonstrated that an ASXL1 mutation alone is not sufficient for inducing the development of hematologic malignancies." (PMID 33292805, 2020).
hematological malignancies (continued). "In this review, we use the term CH rather than clonal hematopoiesis of indeterminate potential (CHIP), as CHIP is defined by a VAF > 2% and by the absence of hematological disease, whereas our discussion includes ASXL1-mutated clones across a broader range of VAFs and clinical contexts.." (PMID 40773119, 2025). "Relationship between AKT3 and mutations related to MDS or MPN hematological disorders The MDS- or MPN-related mutations affect genes involved in different molecular aspects of gene expression including RNA splicing (SRSF2, U2AF1 and SF3B1), chromatin remodeling (ASXL1) and gene transcription (BCOR)." (PMID 38528080, 2024). "Aged Vav-Cre ASXL1-MT KI mice do not develop apparent hematological diseases and their lifetime is equal to wild-type mice." (PMID 33758188, 2021).
cardiovascular disease (9 papers, 2018 to 2025). "Clinical studies in patients with cardiovascular disease have identified DNMT3A, TET2, and ASXL1 genes as the most commonly mutated CHIP-driver genes, accounting for ~80% of all CHIP cases." (PMID 40278194, 2025).
hematologic cancer (7 papers, 2018 to 2021). "As one example, MPN18 harbored hematologic cancer-associated gene mutations in ASXL1, ETV6, and SRSF2 at baseline." (PMID 31911629, 2020). "ARCH/CHIP is mainly associated with mutations in three epigenetic regulatory genes—DNMT3A, TET2, and ASXL1—that have been implicated in hematologic cancers and is a strong risk factor for subsequent hematological cancers." (PMID 33292805, 2020). "It is well known that age-related clonal hematopoiesis is associated with increase in the risk of hematologic cancer and the majority of the variants occurred in three genes: DNMT3A, TET2, and ASXL1." (PMID 29619119, 2018).
neurodevelopmental disorder (4 papers, 2020 to 2026). A behavioral and cognitive disorder with onset during the developmental period that involves impaired or aberrant development of intellectual, motor, or social functions. "The Additional sex combs-like (ASXL1-3) genes are linked to human neurodevelopmental disorders." (PMID 32132929, 2020). "These insights may also facilitate the development of targeted therapies for ASXL1-related neurodevelopmental disorders, including BOS." (PMID 40276524, 2025).
hematological neoplasms (3 papers, 2018 to 2023). "ASXL1 (additional sex combs like 1) is a gene that is mutated in a number of hematological neoplasms." (PMID 30222780, 2018). "It is important to emphasize that the development of cardiovascular diseases can be initiated by mutations associated with blood cancer (DNMT3A, JAK2, ASXL1, and TET2)." (PMID 37726289, 2023). "Mutations in the DNMT3A, ASXL1, and TET2 genes can contribute to the development of blood cancer, and are frequently found in MDS and AML patients." (PMID 37726289, 2023).
infectious disease (1 paper, 2025). A disorder directly resulting from the presence and activity of a microbial, viral, or parasitic agent in humans. "In addition, 3 died from infectious diseases at 1 month (VSAA with WTI variant), 3 months (VSAA with FLT3 variant), and 9 months (VSAA with ASXL1 and IDH1 variant) after diagnosis." (PMID 41477271, 2025).
ASXL1 also shares sentences with these, for which no sentence is quoted: chronic myelomonocytic leukaemia (4 papers); chronic neutrophilic leukemia (4); Splenomegaly (4); trigonocephaly (4); acute lymphoblastic leukemia (3); adrenocortical carcinoma (2); dwarfism (2); endometrial cancer (2); glioblastoma (2); lung adenocarcinoma (2); ovarian carcinoma (2); rectal cancer (2); Stroke (2); acute promyelocytic leukemia (1); adenocarcinoma (1); alcoholism (1); aortic stenosis (1); B-cell lymphoma (1); breast invasive ductal carcinoma (1); cardiac disease (1); chondroblastoma (1); chronic lymphocytic leukemia (1); chronic lymphoid leukemia (1); cleft palate (1); colon adenocarcinoma (1); colorectal adenocarcinoma (1); cutaneous melanoma (1); diffuse large B-cell lymphoma (1); dyslipidemia (1); erythromelalgia (1).
A further 47 diseases each share a sentence with ASXL1 in 1 paper.